TRPV1 (transient receptor potential cation channel subfamily V member 1)
Diseases named in the same sentence as TRPV1 in open-access papers (continued):
Sharing a sentence is not in itself a finding about the gene and the disease.
ileitis (4 papers, 2014 to 2024). "The anti-inflammatory effects of TRPV1 inhibition in the rat colon are similar to those seen in the rat ileum previously and indicate that TRPV1 activation is important in toxin A colitis as well as in ileitis." (PMID 25045574, 2014). "We have previously demonstrated that LTB4 causes ileitis similar to that seen after toxin A administration and that the inflammatory effects of both LTB4 and toxin A are strongly inhibited by TRPV1 antagonism." (PMID 25045574, 2014). "In addition, a decrease in TRPV1 mRNA was found in never smoking patients suffering from Crohn’s ileitis and in the colon of healthy active smokers." (PMID 32760089, 2020). "We have shown previously that LTB4 activates the transient receptor potential vanilloid-1 (TRPV1) ion channel expressed by primary sensory neurons in the ileum resulting in neurogenic inflammation and that inhibition of TRPV1 reduces LTB4- and toxin A-induced ileitis." (PMID 25045574, 2014).
intestinal inflammation (4 papers, 2020 to 2023). "Intestinal inflammation is associated with a parallel overexpression of TRPV1 and S100β along the gut–brain axis (colonic myenteric plexuses, dorsal root ganglion, and periaqueductal grey area)." (PMID 34829900, 2021). "In the DSS-induced intestinal inflammation model, EA at ST36 decreased TRPV1+ ganglion cell expression in S2–3 dorsal root ganglions (DRGs)." (PMID 35095910, 2021).
joint disease (4 papers, 2020 to 2024). "Several authors point to the transient receptor potential vanilloid 1 (TRPV1) ion channel as a possible target for new ways of treating joint disease including OA." (PMID 32197454, 2020). "The TRP vanilloid 1 (TRPV1) ion channel, which is expressed in human and rat synoviocytes, might also be a possible target for treating joint diseases." (PMID 36937015, 2023). "TRPV1 is a potential target for treating joint diseases, including OA, and the present study aims to investigate if the TRPV1 receptor is present in equine articular tissue and determine whether the number of receptors is upregulated in joint inflammation." (PMID 32197454, 2020). "A number of studies have indicated that the TRPV1, which seems to mediate the calcium dependent proliferative and secretory responses of the synoviocytes in the event of joint inflammation, might be a possible and valuable target for treating joint diseases, even in the horse." (PMID 36937015, 2023).
leukemia (4 papers, 2010 to 2023). A malignant (clonal) hematologic disorder, involving hematopoietic stem cells and characterized by the presence of primitive or atypical myeloid or lymphoid cells in the bone marrow and the blood. "To enhance our analysis of TRPV1 expression, we have also performed in silico analyses with datasets 6326/6610 from the Stemformatics database and GSE13159 from the GEO repository, demonstrating its expression in all types of leukemia cells." (PMID 36876044, 2023).
liver fibrosis (4 papers, 2022 to 2024). "TRPV1−/− mice show higher activation of hepatic stellate cells and severe liver fibrosis, while overexpression of TRPV1 has an anti-fibrotic effect." (PMID 38397045, 2024). "This study attributes the anti-liver fibrosis characteristics of TRPV1 to the prevention of hepatic stellate cell activation by recruiting SARM1." (PMID 38397045, 2024). "We have also established a CCl4-induced hepatic fibrosis model using WT or TRPV1−/− mice to evaluate the functional role of TRPV1 in hepatic fibrosis." (PMID 35909891, 2022). "After confirming that TRPV1 KO exacerbated CCl4-induced liver injury and hepatic fibrosis, its expression and function in TGF-β-stimulated HSCs were measured." (PMID 35909891, 2022). "After knocking out TRPV1, CCl4-induced liver injury and hepatic fibrosis aggravated and TGF-β-induced α-SMA and COL1A1 protein expression and HSC proliferation were significantly enhanced." (PMID 35909891, 2022). "Altogether, the obtained data strongly suggest that the correct TRPV1 modulation can improve CCl4-induced hepatic fibrosis and attenuate the effect of TGF-β on HSC activation and proliferation." (PMID 35909891, 2022). "Knocking out TRPV1 significantly increased the expression of various hepatic fibrosis markers, while the expression of these biomarkers declined markedly in capsaicin-activated mice." (PMID 35909891, 2022). "The obtained results indicated that TRPV1−/− had developed an exacerbated phenotype under CCl4-induced hepatic fibrosis." (PMID 35909891, 2022). "In the present study, we demonstrated the detailed function of TRPV1 in the CCl4-induced hepatic fibrosis model of mice and TGF-β-induced HSCs by measurement of liver injury markers, hepatic fibrosis markers, and HSC proliferation." (PMID 35909891, 2022). "The findings suggest that TRPV1 may have a protective impact on liver fibrosis, while TRPV4 may contribute to liver damage by facilitating acetaminophen (APAP) metabolism." (PMID 38255767, 2024). "To further confirm the effect of TRPV1 on CCl4-induced hepatic fibrosis, we evaluated the effect of capsaicin-induced TRPV1 activation and TRPV1 KO on CCl4-induced hepatic fibrosis by measuring the protein expression of fibrosis markers, including α-SMA and COL1A1." (PMID 35909891, 2022). "However, TRPV1−/− mice had more severe hepatic fibrosis whereas capsaicin intraperitoneal injection ameliorated CCl4-induced hepatic fibrosis." (PMID 35909891, 2022). "Finally, our results demonstrated the significant TRPV1 downregulation in human liver fibrosis tissues." (PMID 35909891, 2022). "The obtained results suggest that capsaicin may improve CCl4-induced hepatic fibrosis through activating TRPV1, whereas TRPV1 KO could enhance CCl4-induced hepatic fibrosis." (PMID 35909891, 2022). "Herein, CCl4-induced changes in hepatic fibrosis or liver injury markers could all be attenuated by capsaicin intraperitoneal injection in WT mice, suggesting that capsaicin can activate TRPV1, thereby affecting the effect of CCl4 on hepatic fibrosis." (PMID 35909891, 2022). "In conclusion, our study suggests that TRPV1 may potentially be a promising target for developing new therapeutic strategies to treat hepatic fibrosis." (PMID 35909891, 2022). "In addition, TRPV1 can also alleviate CCl4-induced liver fibrosis and weaken the effects of TGF- β on the activation, proliferation, and apoptosis of hepatic stellate cells, suggesting that the TRPV1 channel may be an effective treatment strategy for liver fibrosis." (PMID 38397045, 2024). "Furthermore, by measuring the protein levels of ECM markers, α-SMA and COL1A1, we revealed that capsaicin can attenuate, whereas TRPV1 KO mice could enhance, the effect of CCl4 on hepatic fibrosis, indicating that TRPV1 plays a protective role against CCl4-induced hepatic fibrosis." (PMID 35909891, 2022).
liver fibrosis (continued). "Taken together, our findings suggested a pathological role of TRPV1 in the development of CCl4-induced hepatic fibrosis, as well as the activation and proliferation of HSC, implying that TRPV1 might be a promising therapeutic target for developing antifibrosis strategies with improved outcomes." (PMID 35909891, 2022).
lung adenocarcinoma (4 papers, 2022 to 2024). A carcinoma that arises from the lung and is characterized by the presence of malignant glandular epithelial cells. "According to research on LUAD (lung adenocarcinoma) patients, TRPV1 expression is notably up-regulated in the tumor tissues, which indicates that TRPV1 might be an alternative novel target for LUAD treatment." (PMID 35806107, 2022).
malaria (4 papers, 2014 to 2020). Malaria is a serious and sometimes fatal disease caused by a parasite that commonly infects a certain type of mosquito which feeds on humans. "Therefore, the impact of TRPV1 ablation in malaria-associated oxidative stress was investigated." (PMID 31223430, 2019). "Repeated subcutaneous administration of the selective TRPV1 antagonist SB366791 after malaria induction increased TRPV1 expression in the brain tissue and enhanced mouse survival." (PMID 31223430, 2019). "It was found that TRPV1 is protective against bacterial infection and modulates the innate immune response to malaria." (PMID 31223430, 2019). "Protection was also observed in mice receiving the TRPV1 antagonist SB366791 repeatedly after malaria was induced." (PMID 31223430, 2019). "On the other hand, the systemic administration of SB366791 in C57BL/6 mice with malaria increased TRPV1 expression (2.1-fold increase) in comparison with vehicle controls." (PMID 31223430, 2019). "Our study provides the first evidence that TRPV1 modulates malaria by mediating innate immune response, specifically by interfering with the expansion and activation of effector cells, especially monocytes." (PMID 25242870, 2014). "Although these results suggest that an intervention with a TRPV1 antagonist may be an alternative to avoid malaria progression, its use should be carefully considered as it may increase mortality upon bacterial infection." (PMID 31223430, 2019). "We used the TRPV1 antagonist, capsazepine, to assess whether TRPV1 is able to modulate the innate immune response to malaria in animals infected with Plasmodium berghei ANKA." (PMID 25242870, 2014). "Overall, TRPV1 antagonism modulates the innate immune response to malaria." (PMID 25242870, 2014). "Herein, the role of TRPV1 in malaria was investigated for the first time." (PMID 25242870, 2014). "We investigated the effects of capsazepine, a TRPV1 antagonist, in malaria." (PMID 25242870, 2014). "However, the impact TRPV1 antagonism may have on severe malaria outcome is of importance and remains to be investigated." (PMID 25242870, 2014). "Also, TRPV1 effects on TNFα production may vary at different stages of malaria." (PMID 25242870, 2014). "More recently, a nonselective TRPV1 antagonist (capsazepine) was found to modulate the peripheral immune response to malaria, but no studies have reported to date, a role for TRPV1 in cerebral malaria development and outcome." (PMID 31223430, 2019). "Here, we show for the first time that TRPV1 antagonism by capsazepine, a nonselective antagonist, modulates the innate immune response to malaria." (PMID 25242870, 2014). "However, we show capsazepine inhibitory effects on these populations do not affect IFNγ production in malaria, indicating that either TRPV1 may not play a role on IFNγ production or NK cells become the sole source of IFNγ once TRPV1 is blocked." (PMID 25242870, 2014).
Malignant hyperthermia (4 papers, 2020 to 2026). Malignant hyperthermia is characterized by a rapid increase in temperature to 39-42 degrees C. Malignant hyperthermia may occur in response to either inhalational anesthetics such as halothane, to muscle relaxants such as succinylcholine, or to exercise. "For example, one study identified two rare TRPV1 variants, T612M and N394del, in patients with malignant hyperthermia (MH), suggesting a potential role in MH pathogenesis." (PMID 41568154, 2026). "The N394del and T612M variants in TRPV1 were identified in malignant hyperthermia (MH) patients exhibiting an increased in vitro sensitivity to the anesthetic halothane." (PMID 39998081, 2025). "TRPV1 acts as a reticular Ca2+-leak channel, and TRPV1 mutations are associated with muscle disorders such as malignant hyperthermia (MH) and exertional heat stroke (EHS)." (PMID 37694792, 2024). "In skeletal muscles, TRPV1 operates as a reticular Ca2+-leak channel and several TRPV1 mutations have been associated with two muscle disorders: malignant hyperthermia (MH) and exertional heat stroke (EHS)." (PMID 33036239, 2020). "This pathophysiological feature associated with TRPV1 variants has also been described in patients with malignant hyperthermia, which manifests with symptoms comparable to heat stroke, such as sudden rise in body temperature, rhabdomyolysis, and loss of consciousness." (PMID 39998081, 2025).
Myocardial fibrosis (4 papers, 2019 to 2025). "In accordance with these findings, isoproterenol-induced myocardial fibrosis was significantly attenuated in transgenic mouse models overexpressing TRPV1." (PMID 40149710, 2025). "Calcium plays an important role in regulating apoptosis, mast gene expression, and myocardial fibrosis, while TRPV1 mediates Ca2+ signal transduction in cells." (PMID 36045746, 2022). "The role of TRPV1 in myocardial fibrosis has been a matter of controversy." (PMID 40149710, 2025). "Moreover, capsaicin attenuated post-AMI inflammation and myocardial fibrosis by activating TRPV1 in diabetic mice." (PMID 40149710, 2025). "Specifically, TRPV1 overexpression substantially reduces isoproterenol-induced proliferation and differentiation in mouse cardiac fibroblasts and prevents the development of myocardial fibrosis." (PMID 36045746, 2022). "Moreover, overexpression of TRPV1 in transgenic mice attenuates isoproterenol-induced myocardial fibrosis, and the activation of TRPV1 has also been shown to be protective in a myocardial injury model." (PMID 31547577, 2019). "Therefore, future work is mandatory to understand whether the pharmacological manipulation of TRPV1 represents a suitable strategy to interfere with myocardial fibrosis." (PMID 40149710, 2025). "However, the contradictory role of TRPV1 in myocardial fibrosis makes it difficult to decide whether TRPV1 should be activated or inhibited when treating inflammation and fibrosis caused by organ damage." (PMID 36045746, 2022). "Emerging evidence suggests that TRPV1, TRPV3, and TRPV4 channels play a crucial role in myocardial fibrosis." (PMID 40149710, 2025). "Furthermore, inhibition of PI3K activity with LY294002 or antagonism of TRPV1 with capsazepine, reversed the protective effect of OEA against DIC in cardiomyocytes, as demonstrated by myocardial fibrosis, cardiac tissue damage and increased number of apoptotic cells." (PMID 35517792, 2022).
oral squamous cell carcinoma (4 papers, 2015 to 2020). "In humans, quantitative expression analysis of TRPV1 has been reported in the lingual mucosa and oral squamous cell carcinoma (SCC)." (PMID 28081185, 2017). "Furthermore, capsazepine reportedly induces TRPV1-independent apoptosis in oral squamous cell carcinoma (OSCC)." (PMID 32604833, 2020). "Hence, we examined the relationship between oral squamous cell carcinoma (SCC) and TRPV1–4 expression." (PMID 28081185, 2017).
papillary thyroid carcinoma (4 papers, 2014 to 2025). "Activation of TRPV1 by capsaicin is associated with inhibition of metastasis in papillary thyroid carcinoma bCPAP cells." (PMID 40007993, 2025). "Furthermore, alteration of TRPV1 activity by capsaicin was shown to significantly reduce the migration and invasion of human papillary thyroid carcinoma BCPAP cells." (PMID 31681615, 2019).
renal carcinoma (4 papers, 2016 to 2022). A carcinoma arising from the epithelium of the renal parenchyma or the renal pelvis. "In human renal carcinoma, capsaicin induces apoptosis that is reversed by the TRPV1 antagonist capsazepine, implying a receptor-mediated mechanism." (PMID 35214061, 2022). "Independent study reported that treatment of a TRPV1 agonist of capsaicin could efficiently reduce proliferation and induce obvious apoptosis of renal carcinoma cells through mediating caspases activation via P38 and JNK within MAPK pathway." (PMID 30881453, 2019). "We found treatment of CPS reduced proliferation of renal carcinoma cells, which could be attenuated by TRPV1 representative antagonist capsazepine (CPZ)." (PMID 27729033, 2016).
sickle cell disease (4 papers, 2012 to 2022). Sickle cell anemias are chronic hemolytic diseases that may induce three types of acute accidents: severe anemia, severe bacterial infections, and ischemic vasoocclusive accidents (VOA) caused by sickle-shaped red blood cells obstructing small blood vessels and capillaries. "A recent study from Xu and colleagues describes that TRPV1-expressing sensory neurons have an important protective role in the hematologic disorder sickle cell disease (SCD)." (PMID 34639197, 2021). "In contrast, in a mouse model of sickle cell disease, incubation of cutaneous C fiber terminals with the same TRPV1 antagonist, A-425619, completely reversed the sensitized mechanical firing in sickle C fibers." (PMID 22927999, 2012). "TRPV1 mediates pain occurring during sickling episodes in sickle cell disease (SCD)." (PMID 34639197, 2021). "However, since TRPV1 is not expressed in most non-nociceptive afferents, it is likely that other molecular mechanisms mediate sensitization of light touch myelinated afferents in sickle cell disease." (PMID 22963123, 2012).
Tinnitus (4 papers, 2008 to 2024). Tinnitus is an auditory perception that can be described as the experience of sound, in the ear or in the head, in the absence of external acoustic stimulation. "These authors suggested that the increases in TRPV1 could be one mechanism underlying the development of tinnitus." (PMID 24861977, 2014). "The authors concluded that upregulated TRPV1 in these ganglia may promote neuronal survival and underlie kanamycin-induced dizziness and tinnitus as side effects." (PMID 19305794, 2008). "Furthermore, TRPV1 may also be implicated in hearing loss associated with inflammation in salicylates-induced tinnitus or in pathological conditions of the inner ear such as in Meniere’s disease or in migraines." (PMID 19305794, 2008). "When TRPV1 channels are antagonized by a specific TRPV1 antagonist (capsazepine), salicylate-induced tinnitus behavior is suppressed." (PMID 35624974, 2022). "A possible explanation for the suppressive effects of GJG on salicylate-induced tinnitus includes mechanisms via the transient receptor potential vanilloid 1 (TRPV1) channel." (PMID 35624974, 2022). "In a rat model of salicylate-induced tinnitus, induction of TRPV1 in the cochlea was observed 2 h following intraperitoneal drug administration." (PMID 24861977, 2014). "Tinnitus can be equated to chronic pain conditions; both involve spontaneous neuronal firing and likely to be mediated via TRPV1." (PMID 19305794, 2008). "The most downregulated genes in the tinnitus (when compared to the non-tinnitus group) were LOC103690064, AABR07048397.1, Trpv1, AABR07061378.1, Ncaph, Spata20, Rps19, Enpp3, Grtp1, and Glra1." (PMID 38562529, 2024).
tongue cancer (4 papers, 2022 to 2025). A malignant neoplasm affecting the tongue. "Moreover, the expression of TRPV1 in the three tongue cancer cell lines (HN6, Cal27, and SCC9) was significantly higher than that in normal oral keratinocytes HOK, with HN6 cells showing the most pronounced difference." (PMID 39132151, 2024). "While we have previously reported increased expression of TRPV1 and TRPA1 in TGs of mice with tongue cancer, we find that TRPV4 was neither abundantly expressed in nerves innervating murine tongue cancer nor in the TGs of mice with tongue cancer." (PMID 40144515, 2025). "Therefore, further experiments are needed to fully characterize its expression in TRPV1- nociceptor and non-nociceptor subtypes, that will provide insights on the whether C1q may be involved in peripheral, secondary or central sensitization during tongue cancer or even other orofacial conditions." (PMID 37573456, 2023).
Acidosis (3 papers, 2014 to 2022). Abnormal acid accumulation or depletion of base. "Acidosis modulates TRPV1 activity, promoting its activation and potentiating its response to 2-APB, heat, and capsaicin (TRPV1 selective agonist)." (PMID 35806388, 2022).